IL6 (interleukin 6)
Diseases named in the same sentence as IL6 in open-access papers (continued):
Sharing a sentence is not in itself a finding about the gene and the disease.
tumor (continued). "Key inflammatory mediators, such as interleukin-6, C-reactive protein and tumour necrosis factor-α, are discussed in the context of their dual role in tumour progression and atherogenesis." (PMID 41235913, 2025). "IL-6 promotes tumor cell survival, and the blockade of IL-6 reduces the side effects of ICIs while enhancing the antitumor immune response, leading to dual effects." (PMID 40040705, 2025). "While curdione and borneol inhibited inflammatory factors such as IL-6 and IL-1β expression in macrophages, TNF-α and CASP1 mRNA expression levels were up-regulated, which are associated with anti-tumor and anti-viral responses." (PMID 39911394, 2025). "Tumor-associated M2 macrophages and their YY1 are highly expressed, and LLPS of the YY1 complex upregulates interleukin (IL)-6 levels in the tumor microenvironment by promoting IL-6 enhancer-promoter interactions, leading to PCa progression." (PMID 40642070, 2025). "High IL6 expression in OC correlates with tumor aggressiveness, driving immune responses such as metastasis and ascites development, as well as contributing to chemoresistance, especially in platinum-based therapies." (PMID 40427188, 2025). "M1 macrophages secrete pro-inflammatory cytokines such as tumor necrosis factor-alpha (TNF-α) and interleukin-6 (IL-6), thereby playing a pivotal role in host defense against pathogens and tumor cells through the modulation of immune responses." (PMID 40710515, 2025). "Functioning as a “conspirator” in tumor development, IL-6 not only promotes the uncontrolled growth and drug resistance of tumors but also facilitates metastasis and colonization, ultimately making cancer more challenging to treat." (PMID 40563367, 2025). "In TNBC, curcumin counteracts the tumor-promoting effects of IL-6, which is known to mediate tumor immune evasion and resistance to vaccine therapy." (PMID 40940890, 2025). "For example, inflammatory factors such as TNF‐α and IL‐6 promote tumor cell invasion and metastasis by activating the epithelial–mesenchymal transition pathway." (PMID 41267926, 2025). "TGFβ has been reported to promote EMT in tumor cells, while TNFα, IL-6, and IL-1 can also promote tumor ETM by upregulating gene expression related to transcription factors such as NF-κB and STAT3." (PMID 39981173, 2025). "Inhibiting IL-6/JAK/STAT3 signaling has been found to slow tumor development and reinstate chemosensitivity." (PMID 40868199, 2025). "IL-6 is a hallmark SASP factor that reinforces the senescent state in an autocrine fashion, while also acting in a paracrine manner to remodel the tumor microenvironment." (PMID 41148817, 2025). "For instance, tumor-secreted IL-6 and M-CSF can transform mature DCs into macrophages and impede the priming of tumor-specific T cells." (PMID 40563367, 2025). "Regarding tumor invasion (pT status), high IL-6 expression was detected in 29 T1–T2, 113 T3, and 17 (36.17%) T4 patients." (PMID 41007818, 2025). "The development into M1 macrophages leads to increased production of pro-inflammatory cytokines (IL1-β, TNF-α, and IL-6), and support of the adaptive anti-tumor activity." (PMID 41440002, 2025). "TNBC-derived EVs also induce macrophage polarization towards an M2 phenotype, creating a tumor-supportive environment via IL-6/STAT3 and NF-κB pathways." (PMID 40103824, 2025). "Compared with surgical margins, tumour tissues showed a characteristic inflammatory shift, with markedly increased IL-1β and IL-6 and relatively reduced TNF-α, IFN-γ, IL-12 and IL-2." (PMID 41465261, 2025). "IL-6 acts as a potent growth factor for EC tumor cells, activating the JAK/STAT3 pathway, which promotes proliferation, survival, and invasion." (PMID 40746533, 2025). "M2b macrophages, activated by immune complexes and LPS, are characterized by their anti-inflammatory profile, releasing IL-10 and IL-6, which dampen anti-tumor immunity." (PMID 40079009, 2025).
tumor (continued). "Stabilization of IL-6 mRNA by m6A promotes tumor proliferation, while aberrant m6A modifications of IL-11 and IL-17RA exacerbate inflammation and metastasis." (PMID 40034695, 2025). "Tumor cell cluster 1 showed enrichment with immunity and cell signaling, involving leukocyte-mediated immunity and production of cytokines and interleukin-6." (PMID 41373592, 2025). "IL-6, a key mediator linking inflammation to tumorigenesis, plays a critical role in PC by enhancing tumor cell survival, proliferation, and immune evasion through activation of STAT3-signalling pathway." (PMID 40872585, 2025). "The increase of IL-6 and IL-8 is a marker of tumor response in the treatment outcome and normal tissue toxicity." (PMID 41220465, 2025). "Due to its central involvement in tumor initiation and advancement, the IL-6/STAT3 pathway is increasingly recognized as a promising focus for small-molecule drug development." (PMID 40723906, 2025). "IL-6 in LC has been found to be secreted by tumor stroma and has been shown to be correlated with a worse prognosis." (PMID 40149994, 2025). "Previous studies have shown that inhibition of IL-6 increased NK cell-mediated killing of human osimertinib-resistant EGFR-mutant NSCLC tumor cells." (PMID 41254082, 2025). "Its activation promotes transcription of anti-apoptotic and oncogenic effectors such as BCL-xL, XIAP, Survivin, and IL-6, thereby enhancing tumor cell survival, proliferation, and chemoresistance." (PMID 40936705, 2025). "Mechanistically, IL-6 promotes tumor growth, metastasis, angiogenesis, immune modulation, and therapy resistance through gp130-mediated signaling." (PMID 40944094, 2025). "Further, there was a trend that a higher neoplasm histologic grade, a higher tumor stage code, and a higher neoplasm disease stage trend towards higher IL6 expression." (PMID 40523922, 2025). "IL-6 secreted by cells in the TME, like cancer-associated fibroblasts (CAFs), tumor-associated macrophages (TAMs), and tumor cells, creates a pro-survival niche that supports TNBC development." (PMID 40868199, 2025). "Interleukin-6 (IL-6) promotes tumor cell proliferation, with its levels significantly elevated during disease progression." (PMID 40606463, 2025). "The relationship between AKT/mTORC1, protein synthesis and AMPK with the cachectic phenotype, tumour development, glucose and IL6 in the LLC fast condition was investigated." (PMID 40931444, 2025). "In contrast, the expression of IFN‐γ, IL‐12, and IL‐6 was significantly reduced in the tumor tissues of mice in the oe‐CXCR4 group." (PMID 40536774, 2025). "Preclinical studies have also shown that IL-6R blockade or genetic ablation of CD8+ T cell intrinsic IL-6 signaling synergized with anti-PD-L1 therapy to enhance antitumor responses, leading to improved tumor control." (PMID 40255422, 2025). "In summary, our findings demonstrate that CAFs promote L-OHP resistance in CRC through IL-6 secretion, fostering a protective tumor microenvironment that enhances cancer cell survival under chemotherapy." (PMID 40718440, 2025). "YTHDF1 inhibits CD8+ T cell cytotoxicity by inducing IL‐6 secretion, allowing tumor cells to evade immune surveillance and inhibiting programmed cell death." (PMID 39802639, 2025). "Macrophages and neutrophils in the tumor microenvironment shape a cytokine milieu (IL-6, IL-1β, TNF, CXCL8) that supports tumor growth and metastasis and counteracts antitumor immunity." (PMID 41440484, 2025). "For example, low levels of IL-6 are beneficial for neuronal survival, while elevated or prolonged IL-6 exposure can promote tumor growth by activating STAT3 signaling." (PMID 40843259, 2025). "IL-6 has also been reported to be relevant to tumorigenesis, stemness in tumor cells, angiogenesis, and metastasis." (PMID 40862837, 2025). "Increased levels of cytokines such as interleukin-6 (IL-6) and tumor necrosis factor-alpha (TNF-α) are observed in HPV-associated cancers, aiding in tumor growth, angiogenesis, and metastasis." (PMID 40006976, 2025).
tumor (continued). "M2 TAMs promote the antiapoptotic ability of tumor cells by secreting IL-6, IL-10 and other cytokines and increase the resistance of tumor cells to chemotherapy drugs." (PMID 40850976, 2025). "Other pro-tumorigenic mechanisms of IL-6 also involve the suppression of tumor senescence, collaboration with other growth factors to amplify malignant behaviors, the induction of EMT, and the promotion of angiogenesis." (PMID 40563367, 2025). "Each output variable in the model represents a measurable biological parameter (such as IL-6 levels in the tumor)." (PMID 40504865, 2025). "NRF2 promotes metastasis by regulating epithelial-mesenchymal transition and modulating cytokine production—suppressing pro-inflammatory cytokines (e.g., IL-6, IL-1β) while inducing tumor-promoting ones like IL-11." (PMID 41187427, 2025). "In parallel to the increased influx of NK cells and NKT cells in GPR4‐deficient animals, we observed a significant reduction of neutrophils and inflammatory monocytes in tumor tissue, accompanied by reduced pro‐inflammatory IL6 levels." (PMID 40397803, 2025). "In GC, IL-6 enhances the proliferation and anti-apoptosis of tumor cells by reshaping the TME, helping them evade the clearance of the immune system." (PMID 41376630, 2025). "In cancer development and progression, IL-6 can promote tumor cell proliferation, anti-apoptosis and angiogenesis by activating JAK/STAT3 and other signaling pathways." (PMID 41376630, 2025). "IL17A recruits and activates neutrophils in the tumor immune microenvironment by inducing the production of IL-6 in their research." (PMID 41254689, 2025). "Nevertheless, the role of CD8+ macrophages in tumor biology and within the context of IL-6 signaling remains to be elucidated." (PMID 39653766, 2025). "For example, IL-6 activates the JAK/STAT3 axis to promote tumor growth and immune evasion, while TNF-α and IL-8 enhance tumor invasion via NF-κB and MAPK signaling." (PMID 41502517, 2025). "Wu and colleagues previously demonstrated that IL-6 and IL-8 secreted by tumor cells play a crucial role in the weakening of NK cell in the context of HNSCC33." (PMID 40883442, 2025). "IL6 was upregulated in both the serum and tumor tissues of patients with HCC and is negatively correlated with poor prognosis." (PMID 39744421, 2025). "Engagement of the CD40 pathway significantly increases the production of pro-inflammatory cytokines like TNF-α, IL-12, and IL-6, which are crucial in driving the anti-tumor immune response and promoting inflammation." (PMID 40055311, 2025). "It is believed that cytokine-mediated processes, specifically the overproduction of interleukin-6 (IL-6) and other pro-inflammatory mediators released by tumour or stromal cells, are responsible for the paraneoplastic inflammatory syndromes linked to GIST." (PMID 41426918, 2025). "SCLC exhibits a unique tumor microenvironment characterized by neuroendocrine features and elevated IL-6 signaling, which drives CRP production and immunosuppression." (PMID 41267986, 2025). "Altogether, this suggests how the synergistic effect of gut-modulated pro-inflammatory cytokines, IL-6/17, in upregulating NLRP3 and associated signaling mechanisms, all of which culminate to progress tumor development at later stages." (PMID 41376623, 2025). "Upregulation of IL6 was observed and its dual immune-modulatory effects involving tumor suppression and microenvironment reprogramming was suggested." (PMID 40746726, 2025). "IL6 is a key cytokine that closely correlates with the tumor size in OC, with its levels significantly elevated in the advanced stages of the disease." (PMID 40427188, 2025). "Compared to HVs, all three neoplasms showed an increased sCD25, sLAG3, Galectin-9 and sB7.2 expression, while gastrointestinal and pancreatic NENs shared higher levels of IL6 and MCP-1." (PMID 40038821, 2025).
tumor (continued). "These bacteria also suppress inflammatory cytokines, including mRNA of NF-κB and IL-6 in the tumor microenvironment, and reduce CD4 + and CD206 + T cells in the spleen, contributing to an anti-tumor immune response." (PMID 40924302, 2025). "GBM cells release IL-6, IL-10, and express PD-L1, fostering T regulatory and myeloid-derived suppressor cell generation, impairing anti-tumor immune responses." (PMID 40106404, 2025). "Pro-inflammatory cytokines such as Interleukin (IL)-1, IL-6, and IL-8 are of particular interest, as they can influence the tumor microenvironment and potentially stimulate immune responses." (PMID 40791595, 2025). "They report that both IL-6 and IL-10 were expressed on TAMs and tumour cells, and that their signalling is critical for disease progression and early relapse in OC patients." (PMID 41463341, 2025). "This is because the IL6-adenosine loop between γδ Tregs and cancer-associated fibroblast (CAF) in human breast cancer accelerates tumor growth." (PMID 40370457, 2025). "The IL-6 secretion upregulated by tumor exosomal cSERPINE2-educated TAMs enhanced CCL2 expression, and thereby, TAMS infiltration into TME was enhanced." (PMID 40443670, 2025). "In particular, we have shown that targeting IL-6 strongly reduces tumor-promoting inflammation and improves tumor burden in a murine KM-LUAD model." (PMID 40356899, 2025). "Based on multivariate regression analysis, BMI, IL-6, and ROS predicted the tumor size, LN stage, and metastatic status of ER+ patients." (PMID 40584290, 2025). "The ELISA results revealed that the culture supernatant from recombinant virus-treated tumor cells significantly increased IL-6 secretion and decreased IL-10 secretion in BMDMs." (PMID 40082916, 2025). "Epigenetic modifications suppress anti‐tumor genes such as RARγ while activating immunosuppressive IL‐6/STAT3 signaling." (PMID 40904700, 2025). "Tumour microenvironment‐driven cytokines, such as IL‐6 and TNF‐α, orchestrate systemic catabolic processes that link muscle wasting to nutritional dysregulation." (PMID 40631494, 2025). "This combined effect in the tumor microenvironment can contribute to immune cell dysfunction and help tumor cells evade the immune system.Conversely, in specific situations, IL-6 and TNF-α can show opposing effects." (PMID 40242775, 2025). "Knockdown of Kindlin-1 leads to reduced recruitment of tumor-infiltrating regulatory T cells (Tregs) and attenuated immunosuppressive activity, primarily through downregulation of interleukin-6 (IL-6) secretion." (PMID 40977686, 2025). "In contrast, iCAFs, which reside farther from tumor nests, secrete large quantities of pro-inflammatory mediators, including IL-6, CXCL12, and LIF." (PMID 41341574, 2025). "Firstly, the tumor microenvironment is known to induce a chronic inflammatory state, characterized by increased production of cytokines such as interleukin‐6 (IL‐6) and other acute‐phase inflammatory proteins such as CRP." (PMID 40791284, 2025). "While IL6 plays two opposing roles in the tumor microenvironment, accumulating evidence establishes IL-6 as a key player in the activation, proliferation and survival of T cells and NK cells during active immune responses." (PMID 40484866, 2025). "The COPD airway is characterized by elevated levels of pro-inflammatory cytokines such as IL-6 and IL-8, and by increased immune cell infiltration, contributing to a tumor-promoting microenvironment." (PMID 41227050, 2025). "Specifically, IL-6 contributes to tumor cell proliferation and the establishment of an immunosuppressive microenvironment." (PMID 41446797, 2025). "Inflammatory mediators such as IL1β, IL6, and MCP-3 (CCL7) not only drive SCC cell growth but also recruit and condition myeloid populations, including monocytes, tumor-associated macrophages, and MDSCs, thereby promoting a suppressive, tumor-permissive niche." (PMID 41510255, 2025).
tumor (continued). "Although senescent cells are growth-arrested, senescent fibroblasts release a range of cytokines—such as IL-6, IL-1β, and MMPs—that profoundly reshape the microenvironment and promote tumor cell proliferation and invasion." (PMID 41476608, 2025). "In our study, when their expression was induced by tumours, Upd3 and IL-6 promote gluconeogenesis gene expression through activation of hepatic JAK–STAT signalling in both mouse and fly models." (PMID 40275022, 2025). "Specifically, enteric glial cells within the tumour secrete IL‐6, which induces infiltrating monocytes to differentiate into SPP1‐expressing TAMs." (PMID 40395129, 2025). "Cytokines, including TNF-α, IL-10, IL-8, and IL-6, are also released by the tumor stroma, and are identified as chemotactic, immunosuppressive, and pro-survival signals, further supporting EMT induction." (PMID 39941895, 2025). "M1 macrophages typically contribute to anti-tumor immunity by engaging in antigen presentation and producing proinflammatory cytokines like interleukin-6 (IL-6), interleukin-12 (IL-12), and interleukin-1 (IL-1)." (PMID 40302816, 2025). "Tumor-secreted factors like PTHrP and IL-6 upregulate RANKL in osteoblasts, creating a “vicious cycle” of bone resorption and tumor growth." (PMID 40680227, 2025). "TAMs were previously shown to activate the JAK2/STAT3 pathway through IL-6, inhibit tumor suppressor miRNAs like R-506-3p and its target FoxQ1, secrete CCL22, and activate the PI3K/AKT pathway." (PMID 40607405, 2025). "Both IL-1 and IL-6 play pivotal roles in creating a tumor-promoting microenvironment, with chronic inflammation fostering DNA damage, cellular proliferation, and immune suppression, all of which contribute to cancer progression." (PMID 40791595, 2025). "In summary, our work affirms the strong connection between IL-6 and the immunosuppressive tumor microenvironment in ESCC." (PMID 40433391, 2025). "Th2 cells primarily secrete IL-4, IL-6, and IL-10; IL-4 regulates MDSCs by synthesizing arginase 1 (Arg1) and decomposing l-arginine to induce T-cell apoptosis and tumor immunosuppressive effects." (PMID 41278263, 2025). "Systemic inflammation, driven by proinflammatory cytokines such as tumor necrosis factor-α (TNF-α), interleukin (IL)-6, and IL-1β, produced by both the tumor and the host, is involved in the pathogenesis of cancer cachexia." (PMID 40136406, 2025). "They showed that tumor-derived exosomes promote the production of pro-inflammatory mediators, where NF-κB activation leads to IL-6 production, a prerequisite for subsequent STAT3 activation in an autocrine or paracrine way." (PMID 40443670, 2025). "Excess secretion of pro-inflammatory cytokines (e.g. IL-6, IL-1β, TGFα) by immune cells is critically involved in tumour cell avoidance of immune surveillance in the tumour microenvironment as well as in inflammation." (PMID 41023585, 2025). "Then P2RX7 participates in cell proliferation and tumor metastasis by inducing cells to secrete cell cytokines such as interleukin-6." (PMID 41007849, 2025). "The IL6‐JAK‐STAT3 signalling pathway has a significant impact on various BPs in tumours, such as migration, invasion and angiogenesis." (PMID 39893643, 2025). "One study found that FTO works by inhibiting growth and glycolysis, likely by reducing the expression of APOE which acts to promote tumor growth via the IL-6/JAK2/STAT3 pathway." (PMID 40243425, 2025). "Among these, IL-6 has been associated with poor chemotherapy response, in part by regulating autophagy and promoting BECN1 phosphorylation, which strengthens tumor survival under treatment stress." (PMID 41155372, 2025). "IL-6 promotes tumor growth, immune modulation, and inflammation by activating STAT3 pathways, which maintain constitutive nuclear factor-κB (NF-κB) signaling." (PMID 40227644, 2025). "Inflammation plays a critical role in HNC progression, with elevated levels of pro-inflammatory cytokines such as TNF, IL-6, IL-8, and IL-1β contributing to tumor development." (PMID 40733296, 2025).